MMP9 (matrix metallopeptidase 9)
Diseases named in the same sentence as MMP9 in open-access papers (continued):
Sharing a sentence is not in itself a finding about the gene and the disease.
tumor (continued). "Many molecular–genetic studies conducted in various tumor types have revealed a frequent association of the T allele with increased levels of MMP-9 as well as with hallmarks of tumor progression." (PMID 36010303, 2022). "Treatment of CC mice with selective human and mouse antibody inhibitors of MMP9 caused significantly reduced tumor growth and incidence of metastases in comparison with the isotype controls." (PMID 35406619, 2022). "A number of studies have shown that the high expression of MMP9 is associated with the improvement of tumour migration and invasion ability." (PMID 35557941, 2022). "In cancer, higher MMP-2 and MMP-9 activities have been linked to not only tumor cell invasion but also angiogenesis." (PMID 35625802, 2022). "We find the MMP9+ macrophages to be terminally differentiated tumor-associated macrophages (TAMs) and PPARγ to be the pivotal transcription factor driving their differentiation." (PMID 35933472, 2022). "CyclinD1 is one of the key cell cycle regulators, and MMP9 expression is closely associated with the invasion and migration of tumor cells." (PMID 35023214, 2022). "In an animal model of UM, curcumin treatment resulted in lowered expression of MMP-2 and MMP-9 at both the mRNA and protein level in cancer cells, causing a reduction in tumor size." (PMID 35457074, 2022). "The signaling pathway members were upregulated in the IORT of tumor bed14, so NF-kB can cause enhancing MMP-9 in cells affected by WF." (PMID 35538133, 2022). "MMP2 and MMP9, which degrade type IV collagen and gelatin substrates, are highly associated with tumor dissemination, angiogenesis, and invasiveness in various solid tumor types." (PMID 35449123, 2022). "Highly expressed MMP-9 has been found in EC tissues, and is associated with poor prognosis, tumor size and clinical staging." (PMID 35578338, 2022). "Matrix metalloproteases, including MMP-9, are linked to progression in many cancers and are responsible for the remodeling of the extracellular matrix, resulting in tumor invasion and metastasis." (PMID 35267943, 2022). "It was observed that MMP9-deficient mice were characterized by decreased levels of circulating tumstatin linked to an increased rate of tumor growth, and this effect was reversed upon restoration of the physiological concentration of tumstatin in blood." (PMID 35406619, 2022). "While the awakening of tumor cells is associated with neutrophil elastase and MMP9, which induce the proliferation of dormant CTCs by exposing laminin epitopes associated with CTCs." (PMID 36237333, 2022). "It has been reported that MMP-9 can regulate tumor growth and promote malignant cell invasion and is associated with a poor prognosis." (PMID 34122670, 2021). "In the literature, a high expression of MMPs, especially MMP-9, has been linked to poor prognosis in several tumor types often associated with an increased risk of invasion and metastasis." (PMID 33808256, 2021). "TGFβ in the tumor microenvironment can induce the polarization of N2 tumor-associated neutrophils and produce a large amount of MMP-9 and VEGF." (PMID 34327245, 2021). "MMP‐9 is predominantly secreted by inflammatory cells such as tumor‐associated macrophages, which are found at the sites of pathological angiogenesis and are important for tumor angiogenesis." (PMID 34647412, 2021). "It was consistent with a study on MMP9-deficient mice showing that the loss of MMP9–cell surface interactions dramatically decreases tumor cell motility and invasiveness." (PMID 33572115, 2021). "The next studies confirmed that overexpression of MMP-9 in tissue was associated with a higher risk of tumour recurrence and poor prognosis." (PMID 33923108, 2021). "Assessment of the MIR4435-2HG/hsa-miR-1-3p/MMP9/hsa-miR-29-3p/DUXAP8 ceRNA network axis in HCC showed that a high risk/poor prognosis was significantly correlated with tumor stage and invasion depth." (PMID 35201491, 2021).
tumor (continued). "Another factor important for vasculogenesis is matrix metalloproteinase-9 (MMP9), a downstream factor of HIF1α produced by recruited myeloid cells and tumor-associated inflammatory and stroma cells." (PMID 33921099, 2021). "MMP9 has been found to play an essential role in cancer progression and is significantly associated with metastasis, angiogenesis, and tumor growth." (PMID 34587931, 2021). "EMT‐associated TF Snai1 and tumor invasive marker MMP‐9 showed elevated expression in the FSS‐HepG2 cells." (PMID 34260811, 2021). "MMP9 expression has been associated with loss-of-tumor suppression activity, as well as with gain-of-oncogenic activity." (PMID 34503132, 2021). "After MMP-9 mediated activation, both antibody variants induced tumor cell killing comparable to trastuzumab." (PMID 34413859, 2021). "MMP-2 and MMP-9 have also been associated with tumor stage, lymphatic invasion, lymph node metastasis, and recurrence." (PMID 33773545, 2021). "MMP-9 (gelatinase-B) is most commonly linked with tumor migration, invasion, and metastasis in a variety of human cancers." (PMID 34073059, 2021). "High expression of MMP-2, MMP-9, and both has been associated with tumor progression and poor survival of HCC patients." (PMID 34819565, 2021). "These chemokines also recruit tumor-associated neutrophils (TAN) to the tumor niche —cells that secrete MMP-9 into the tumor microenvironment; MMP-9 is a metalloproteinase that causes a VEGF release from the extracellular matrix (ECM)." (PMID 34639040, 2021). "Here, tumours homozygous for the wild-type alleles of MMP9 rs2236416 and rs2274755 showed a median PFS of 9.48 months, and carrying at least one variant allele led to a reduced median PFS of 6 and 6.62 months, respectively (p = 0.022, p = 0.043, respectively)." (PMID 33573134, 2021). "Increased expression of CDH2, CTSB, ACTA2, MMP2 and ZEB1 was associated with increased myometrial invasion, and expression of CTSB and MMP9 was significantly associated with tumor recurrence." (PMID 34936030, 2021). "MMP9 is a well-known oncogenic gene, and the enzyme encoded by this gene is involved in multiple processes in tumour progression, such as cancer proliferation, angiogenesis and metastasis." (PMID 33892730, 2021). "It has been reported that MMP9 can also stimulate tumor growth, while cancer cell proliferation is decreased in tumors from MMP9-deficient mice compared with wild-type mice." (PMID 34239873, 2021). "High IGFBP1 was associated with lower GC metastasis and inhibited the tumor cell migration and invasion owing to decreasing MMP9 expression in GC cells." (PMID 33931579, 2021). "The tumor-stromal crosstalk mediated by various cytokines and growth factors enhances the expression of MMP-9 which causes altered proteolysis." (PMID 34707964, 2021). "TSPAN9 suppresses the ERK1/2 pathway to downregulate the proteins associated with tumor metastasis including matrix metalloproteinase-9 (MMP-9) and urokinase plasminogen activator (uPA)." (PMID 34222025, 2021). "The overexpression of MMP9 is a potential biomarker in cancer, because MMP9 promotes the development and progression of cancers, is associated with tumor growth, and mediates tumor invasion, metastasis, and the tumor microenvironment." (PMID 34577904, 2021). "MMP-9 plays important roles in degrading extracellular matrix and loss of epithelial cell integrity, and is closely related to tumour invasion and metastasis." (PMID 34262419, 2021). "We also found that NRF2 MTs induce the transcriptional activity of the MMP9 promoter, thereby driving increased MMP9 expression that is linked to tumor invasion." (PMID 34069882, 2021). "NF-κB-promoting proinflammatory mediators, associated with tumor growth and antiapoptotic molecules (i.e.,MMP-9, CXCR4, Ki-67, β1-integrin, and Caspase-3) and its translocation to the nucleus in HCT116 cells, were increased in both TME cultures." (PMID 34660256, 2021).
tumor (continued). "Upregulation of MMP2 and MMP9 is highly associated with tumor progression; thus, both of them are regarded as potential targets for cancer therapy." (PMID 33958583, 2021). "This antitumor effect resulted from the cytotoxic/apoptotic effect of paclitaxel on tumor cells (activating caspase-3/7 activity) and a proteolytic remodeling of the extracellular matrix by regulation of collagen IV disposition and MMP-9 caused by E-3810." (PMID 34948368, 2021). "Studies show that MMP-2 and MMP-9 deficient mice show impaired tumor cell growth and poor metastasis." (PMID 33841500, 2021). "Our analysis demonstrated that MMP9 overexpression was associated with poorer OS, larger tumor size, and higher TNM stage in TNBC, suggesting the promising role of MMP9 in the prognosis of TNBC." (PMID 33568081, 2021). "Exosomes also express proteins from the dipeptidyl-peptidase IV (DPP IV) and MMP9 families, involved in the extracellular matrix remodeling, representing the reason why exosomes are associated with tumor invasion and metastasis." (PMID 33919272, 2021). "It is well documented that decreased PCNA and CCND1 expression is associated with retarded proliferation of tumor cells and that reduced MMP9 and Vimentin expression is closely related to slowed invasion of cancer cells." (PMID 34511432, 2021). "MAPK7 loss in xenograft tumours reduces MMP9 expression in TAMs that have intact MAPK7, further supporting our assertion that MAPK7 signals dictate TAM behaviour and phenotype." (PMID 32655131, 2020). "Except from their established role in host-pathogen interactions, NETs modulate cancer-associated procoagulant activity and promote tumor growth by including tumor-promoting components such as MMP-9, cathepsin G and neutrophil elastase." (PMID 33363012, 2020). "The two MMP-2 and MMP-9 have been associated with the malignant phenotype of tumor cells because of their unique ability to degrade type IV collagen, which is a major component of the basement membrane." (PMID 32353975, 2020). "Conversely, high expression of MMP-9 in the stroma and the tumor was associated with higher survival rates than low expression." (PMID 32669083, 2020). "MMP-9 degrades the extracellular matrix of cells and caused tissue disruption for the invasion of tumor cells in the metastasis process." (PMID 32526880, 2020). "MMP-9 was elevated in the urine samples of BC patients and has been associated with tumor growth, invasion and metastasis." (PMID 32922663, 2020). "These T-EVs have been revealed to trigger DCs and cause IL-6 secretion, which enhances tumour invasion by increasing MMP-9 metalloproteinase expression." (PMID 33081785, 2020). "MMP-9 is the most detected in a variety of malignant tissues and is associated with tumor metastasis and recurrence potential." (PMID 32143570, 2020). "Gelatinases MMP-2 and MMP-9 have been implicated in many pathophysiological processes, such as tumor invasion and metastasis, but there are limited studies on the role of MMPs in mediating symptoms in patients undergoing adjuvant RT." (PMID 33134822, 2020). "Platelets secrete CXCL5 and CXCL7, contact with tumor cells cause recruitment of granulocytes (CD11b+MMP9+Ly6G+) to tumor cells in lung to form early metastatic niches directly helping in tumor cell seeding and development of lung metastases." (PMID 33414786, 2020). "Next, in order to estimate the effect of SM on the expression of markers associated with EMT and tumor cell invasion in the metastatic foci, fluorescence-based immunohistochemistry for E-cadherin and MMP-9 was performed." (PMID 33327637, 2020). "The expression of HMGB1 was also positively and significantly associated with tumor expression of mRNA encoding the pro-invasive, proteolytic enzyme, matrix metalloproteinase 9 (MMP-9), both of which correlated significantly with metastatic potential." (PMID 32664328, 2020).
tumor (continued). "Combined MMP9 cytoplasmic and stromal (CS) survival analysis demonstrated that tumours with high cytoplasmic and stromal expression were associated with poor prognosis (p = 0.008; HR = 1.2; 95%CI 1.0–1.4)." (PMID 32445177, 2020). "Elevated MMP9 protein levels were associated with high tumour grade, high Nottingham Prognostic Index, and hormonal receptor negativity." (PMID 32445177, 2020). "Our findings also confirm another result, a positive correlation between MT-2A and MMP-9, suggesting the associated participation of these proteins in tumor invasion." (PMID 31936364, 2020). "For example, studies have exhibited that MMP-9 is profoundly implicated in the invasion, metastasis, and angiogenesis of various tumors and can mediate the tumor microenvironment." (PMID 32698816, 2020). "MMP-2 and MMP-9, both gelatinases, have been associated with tumor progression and tumoral angiogenesis, but in our analyses, MMP-9 had a different pattern of association." (PMID 32669083, 2020). "Among the MMP family members, the gelatin-degrading enzymes MMP-2 and MMP-9 are associated with tumor ability to invade as their expression levels are often upregulated in the advanced stages of cancer." (PMID 32984054, 2020). "It is well established that MMP-9 is profoundly implicated in the invasion, metastasis, and angiogenesis of various tumors and can mediate the tumor microenvironment." (PMID 32698816, 2020). "Among these genes, four genes (TIMP1, MAPK13, MAPKAPK2 and MAPKAPK3) are known to regulate cell proliferation, and MMP2 and MMP9 control tumour-associated tissue remodelling; PIK3CD is involved in the immune response, and AKT2 regulates tumourigenesis." (PMID 32999349, 2020). "These macrophages mediate the loosening of vascular junction and enhance vascular permeability and MMP-9 expression by tumor-associated neutrophils." (PMID 32974184, 2020). "Specifically, MMP-9 regulation is positively modulated via the binding activity of transcription factors NF-κB, Sp-1, and AP-1 during tumor-associated migration and invasion." (PMID 32708058, 2020). "Different microglial-derived factors including proteases (e.g., Ctss, Mmp3, and Mmp9), Wnt signaling components or chemokines (e.g., Cxcl12) have been implicated in assisting tumor cells to cross the BBB and colonize the brain parenchyma." (PMID 33384994, 2020). "MMP9 deficiency on the Kras(G12D) background enhanced tumor progression and invasive growth, supporting this notion and providing an alternative explanation for the negative marimastat and BAY 12-9566 results in PDAC patients." (PMID 32325664, 2020). "The anti-metastatic effect of compound 9 was associated with the inhibition of MMP-2 and MMP-9, two zinc-dependent endopeptidases associated with tumor invasion and metastasis, as well as the induction of angiogenesis." (PMID 32751120, 2020). "It is known that higher MMP2 and MMP9 and lower laminin and fibronectin are associated with migration and invasion of tumor cells." (PMID 33519431, 2020). "The gelatinases MMP-2 (gelatinase A) and MMP-9 (gelatinase B) are two members of the MMP family that are known to be associated with tumor invasion, metastasis and progression." (PMID 32024881, 2020). "Reports published in the literature indicated that MMP-2 can enhance the migration of HCC cells by increasing fibronectin cleavage and that the overexpression of MMP-9 is associated with HCC tumor migration and invasion." (PMID 32549236, 2020). "IL-6 secreted by endothelial cells within the prostate TME are also capable of promoting tumor invasiveness and metastasis via MMP9 activation by causing tumor remodeling." (PMID 32585812, 2020). "Increased MMP9 expression is associated with enhanced tumor invasion properties; therefore, we ascertained the effect of Celecoxib on MMP9 promoter activity in HCC cells." (PMID 33194674, 2020). "MMP9 produced by neutrophils in the tumor microenvironment was also found to be strongly associated with the tumor angiogenesis." (PMID 33343560, 2020).
tumor (continued). "Subsequently, the protein expression level of N-cadherin, Vimentin, MMP-2 and MMP-9 associated with metastasis ability of tumor were detected to further determine the effect of different treatments." (PMID 31391034, 2019). "Upregulation of MMP-9 expression can degrade various components of the extracellular matrix and destroy the histological barrier, causing the tumor progression and invasion." (PMID 30704487, 2019). "Upregulation in MET can increase Matrix Metalloproteinase 9 (MMP-9) production by tumor-associated stromal cells, and blocking MET can significantly reduce MMP-9 activity." (PMID 30631034, 2019). "Tumor-associated neutrophils (TANs) contribute to tumor intravasation by inducing neovessel formation via MMP-9." (PMID 31835465, 2019). "We found a downregulation in mmp9 mRNA levels in ody and a reduction in neutrophil motility in tumor-naïve cxcr4b deficient zebrafish embryos." (PMID 30787324, 2019). "Overexpression of MMPs particularly MMP-2 (Gelatinase A) and MMP-9 (Gelatinase B) has been associated with tumor progression, metastasis, and poor prognosis." (PMID 31817718, 2019). "Gelatinases (MMP-2 and MMP-9) have been implicated in the induction of the angiogenic switch in different tumor models." (PMID 30792527, 2019). "Emerging literature reveals the association of CD44 with MMP-9 in mouse and human tumor cells to enhance the invasion of cancer cells." (PMID 31579438, 2019). "In RCCs, overexpression of MMP-1, MMP-2, and MMP-9 is linked to tumour stage, histological grade, progression, invasion of microvasculature, and distant metastasis." (PMID 31771219, 2019). "Anti‐MMP9 antibody increased the levels of tumour‐associated IL‐28 (1.5‐fold) and decreased stromal markers (collagen I, αSMA) and the EMT marker vimentin." (PMID 30941918, 2019). "The overexpression of MMP-2 and MMP-9 is associated with pro-oncogenic events such as neo-angiogenesis, tumor cell proliferation, and metastasis." (PMID 31402861, 2019). "The increased expression of MMP-2 and MMP-9 within tumor decreases the risk of metastases to cervical lymph nodes in the initial stage of the disease." (PMID 31223594, 2019). "Previous reports suggested that the interaction between HMGB1 and RAGE triggered the activation of NF-κB, MAPK, and MMP-2/MMP-9 signaling pathways, which are associated with tumor growth, invasion, and metastasis." (PMID 29850505, 2018). "Co-culturing macrophages with tumor cells caused increased expression of MMP-7 and MMP-9 in the tumor cells." (PMID 29731961, 2018). "In this report, we explored the mechanism by which MMP-9 promotes tumorigenesis using a variant of this NeuT syngeneic tumor model where MMP-9 is expressed predominantly by myeloid cells." (PMID 30500835, 2018). "Recent studies have implicated that radiation-induced MMP-9 led to enhanced tumor growth and metastasis." (PMID 29743497, 2018). "Recent studies have also implicated the tumor-fibroblast interactions in tumor angiogenesis by increasing expression in tumor cells of MMP9 and pro-angiogenic growth factors such as VEGFA and HB-EGF." (PMID 29921235, 2018). "More than 20 MMPs have been described and MMP-2 and MMP-9 are strongly associated with tumor spread and invasiveness." (PMID 30235848, 2018). "Stable loss of SMAD4 in microglia decreased expression level of a tumor promoter, MMP9, which resulted in decreased migratory potential of microglia in a transwell migration assay." (PMID 29861845, 2018). "A high production of MMP-2 and MMP-9 increases the migration and invasion of tumor cells and is associated with a poor prognosis in cancer patients." (PMID 30235848, 2018). "Matrix metallopeptidase (MMP)-9, also known as gelatinase B, is widely associated with tumor progression because of its role in extracellular matrix (ECM) remodeling, angiogenesis, and neovascularization." (PMID 30139373, 2018).